PAX2 (paired box 2)
Diseases named in the same sentence as PAX2 in open-access papers (continued):
Sharing a sentence is not in itself a finding about the gene and the disease.
breast carcinoma (continued). "Breast cancer patients with luminal tumors expressing PAX2 might be responding better to Tam in comparison to patients with undetectable PAX2 expression." (PMID 32843722, 2020). "Notably, PAX2 is overexpressed in >50% of breast cancers and was required for progesterone-stimulated lateral side-branching and lobular development in a murine Pax2-knockout model." (PMID 28412963, 2017). "Identification of phosphorylated receptors in human tumors and discovery of phospho-PR-regulated pathways (i.e., including HER2, RUNX2, AR, AHR, and PAX2) suggest novel ways to specifically target breast cancer stem cell (CSC) outgrowth as part of durable breast cancer therapies." (PMID 28412963, 2017). "Moreover, in luminal breast cancer cell lines, PAX2 has been shown to be activated and confers a low invasive phenotype." (PMID 23192763, 2013). "Our results show that in response to estradiol, PAX2 is phosphorylated and activated in breast cancer cells of the luminal subtype selectively, via ERα; further, modulation of PAX2 expression in these cells directly impacts their invasive ability, in an ERα-dependent manner." (PMID 22168360, 2011). "The presence of PAX2 in breast tumours has been described many years ago, but the role of the transcription factor in these tumours remained unknown until recently, when PAX2 was shown to dictate the response of luminal breast cancer cells to tamoxifen." (PMID 22168360, 2011). "Available clinical data indeed suggests an inverse relationship between PAX2 activity and the proliferation of breast cancer cells in vivo: lower PAX2 immunoreactivity can be detected in the nucleus of cells from high grade breast tumours compared to low grade tumours." (PMID 22168360, 2011). "Finally, we have identified a first negative regulator of PAX2 activity in luminal breast cancer cells, IGF-1." (PMID 22168360, 2011). "Silencing of PAX2 led to an increase in SRC-3/AIB1 bound to the HER-2 enhancer and significantly higher levels of HER-2 mRNA levels during tamoxifen treatment in breast cancer cell lines." (PMID 22703232, 2012). "The study demonstrates that PAX2 activation by estradiol is selectively achieved in breast cancer cells of the luminal subtype, via ERα, and identifies IGF-1 as a negative regulator of PAX2 activity in these cells." (PMID 22168360, 2011). "Altogether, these results strengthen the inverse relationship between PAX2 activity and cellular invasion and identify IGF-1 as a negative regulator of PAX2 activity in luminal breast cancer cells." (PMID 22168360, 2011). "Given the results that some of the PAX2 genes are regulated by IRF1 and the expression of IRF1 predicts survival in breast cancer patients, we examined whether PAX2 was able to induce apoptosis through IRF1 in MCF-7 cells." (PMID 32843722, 2020). "We have then determined the impact of estradiol exposure on the activation status of PAX2, in luminal and non-luminal breast cancer cell lines." (PMID 22168360, 2011). "A putative role for PAX2 as a negative regulator of invasion and metastasis in breast cancer cells, however, has not been pursued to this day." (PMID 22168360, 2011). "The inhibition of anti-invasive factors such as PAX2 may contribute to the pro-invasive and pro-metastatic effects of IGF-1 in breast cancer cells." (PMID 22168360, 2011). "PAX2 activity was higher in cell lines from luminal compared to non-luminal subtype, and activation of PAX2 by estradiol was selectively achieved in breast cancer cell lines of the luminal subtype." (PMID 22168360, 2011). "Supporting this hypothesis, a recent study has revealed that PAX2 negatively regulates the expression of a well-established pro-invasion and pro-metastastic gene, ERBB2, in estradiol-treated luminal breast cancer cell lines." (PMID 22168360, 2011).
breast carcinoma (continued). "Since estradiol treatment had no impact on PAX2 expression, at the protein or mRNA levels, these results indicate that estradiol specifically regulates the activation of PAX2 protein, but not PAX2 expression, in luminal breast cancer cells." (PMID 22168360, 2011). "In the present study, we have characterized the regulation of PAX2 expression and activation in luminal and non-luminal breast cancer cells; we also examined how the modulation of PAX2 expression affects the invasiveness of estradiol-treated luminal breast cancer cells." (PMID 22168360, 2011). "Therefore, transcription would not be a major level of regulation for PAX2 in breast cancer cells, compared to post-translational modification of the protein." (PMID 22168360, 2011). "Therefore, we can realistically envision future combination therapies, designed to re-express ERα and to overexpress PAX2 at the same time in non-luminal breast cancer cells, capable of efficiently interfering with progression of the disease towards metastasis." (PMID 22168360, 2011). "The cooperation between PAX2 and EZH2 has been confirmed to be abnormally expressed in ovarian cancer, whereas not reported in breast cancer." (PMID 36318256, 2023).
optic nerve colobomas (11 papers, 2009 to 2025). "Genetic causes of CAKUT have been revealed since 1995 when a mutation in PAX2 was first discovered to cause optic nerve coloboma, renal hypodysplasia, and vesicoureteral reflux." (PMID 32164334, 2020). "Ocular involvement is present in patients with PAX2 mutations, and bilateral optic nerve coloboma is typically associated with RCS." (PMID 26571382, 2015). "She and her son (Patient 2, 18 years of age) had bilateral optic nerve coloboma, and they each had the same PAX2 mutation." (PMID 26571382, 2015). "Our data reveal that optic nerve coloboma was more severe in patients with PAX2 mutations." (PMID 26571382, 2015). "However, the degree of optic nerve coloboma varied between patients or between each eye of an individual, although patients had the same PAX2 mutation." (PMID 26571382, 2015). "Variants within PAX2 could result in optic nerve colobomas and kidney hypoplasia." (PMID 35444690, 2022). "A review of reported cases of PAX2-related optic involvement summarized the most common ocular findings, which included optic nerve coloboma, optic disc excavation or pit, optic nerve hypoplasia, abnormal retinal vessels, strabismus, and retinal vessel abnormalities." (PMID 40282888, 2025).
prostate carcinoma (11 papers, 2008 to 2025). A carcinoma that arises from epithelial cells of the prostate gland. "In an in vitro invasion model using prostate cancer cells 22Rv1 and DU145, PAX2 overexpression promoted prostate cancer cell invasion, which was associated with upregulated N-cadherin expression." (PMID 37511191, 2023). "In the present work, we provide evidence that EN2 is aberrantly expressed in prostate cancer and is regulated by the PAX2 transcription factor that promotes prostate cancer cell growth and survival." (PMID 21566742, 2008). "Our previous studies demonstrated that PAX2 expression is an essential requirement for prostate cancer cell survival." (PMID 21566742, 2008). "Silencing of PAX2 expression in prostate cancer cells results in re-expression of HBD1." (PMID 30575780, 2018). "In addition, PAX2 has been shown to be aberrantly over-expressed in urogenital cancers, including prostate carcinomas." (PMID 21566742, 2008). "Furthermore, we found a positive correlation between EN2 and PAX2 where prostate cancer cells exhibiting decreased EN2 expression also possessed decreased PAX2 levels." (PMID 21566742, 2008). "Therefore, from our studies we conclude that En-2 is a candidate oncogene in prostate cancer and its PAX2-regulated expression contributes to prostate cancer cell growth." (PMID 21566742, 2008). "QRT-PCR analysis of PAX2 was performed in LNCaP cells after treatment with EN2 siRNA to determine whether En-2 can modulate PAX2 expression in prostate cancer." (PMID 21566742, 2008). "Additional oncogenic cascades activated by Ang II include PAX2, STAT3, and JAK2 in prostate cancer and RAS/RAF/ERK1/2 in gastric malignancies." (PMID 40722848, 2025). "GATA2 has been reported to directly upregulate IGF2 in chemo-resistant prostate cancer, while IGF2 activity leads to PAX2 overexpression in Wilms’ tumor, suggesting a possible signalling axis in NET-PATZ1." (PMID 34417833, 2021). "Suppression of PAX2 expression with concomintant EMT-related changes might be applicable to multiple cancer types in which PAX2 is expressed, including RCC, ovarian, breast, endometrial and prostate cancer." (PMID 29928489, 2018). "Western blot analysis of EN2 protein expression in the prostate cancer cell lines after 3 days of PAX2 siRNA treatment demonstrated that EN2 expression was decreased 70% in PC3 (lane 2) and 26% in LNCaP (lane 4) prostate cancer cell lines as compared to PC3 (lanes 1) and LNCaP (lanes 3) controls." (PMID 21566742, 2008). "Furthermore, we found a positive correlation between En-2 and PAX2 genes in prostate cancer cell lines, where cells exhibiting decreased EN2 expression also exhibited a down regulation of PAX2 expression level." (PMID 21566742, 2008).
melanoma (10 papers, 2009 to 2025). A malignant, usually aggressive tumor composed of atypical, neoplastic melanocytes. "Interestingly, in tissue sections of melanoma patients nuclear PAX2 expression strongly correlated with nuclear atypia and the degree of prominent nucleoli, indicating an association of PAX2 with a more atypical cellular phenotype." (PMID 21876729, 2011). "The PAX2 gene plays a vital role in ADAM10 expression, and it has been observed that increased ADAM10 expression via upregulation of PAX2 is associated with melanoma metastasis, attributed to the metalloproteinase activity of the ADAM10 gene." (PMID 29201043, 2017). "The shedding of EGFR ligands is mainly dependent on the metalloproteases ADAM-17 and ADAM10, the latter being induced by PAX2 in melanoma." (PMID 24970815, 2014). "To investigate the role of PAX2 in melanoma development, we analyzed its expression in normal melanocytes and melanoma cells and in tissue samples of benign nevi and melanoma." (PMID 21876729, 2011). "To determine the expression of PAX2 in human skin tissue we performed immunohistochemistry analysis on tissue sections of benign nevi and malignant melanoma." (PMID 21876729, 2011). "We found weak PAX2 expression in melanocytes and keratinocytes, but increased PAX2 levels in melanoma cell lines." (PMID 21876729, 2011). "In this study, we investigated PAX2 protein levels in melanocytes and melanoma cells by Western Blot and immunofluorescence analysis and characterized the role of PAX2 in the pathogenesis of melanoma." (PMID 21876729, 2011). "Another important aspect of our study is that the downregulation of PAX2 in melanoma cells abrogated the chemoresistance of melanoma cells against cisplatin." (PMID 21876729, 2011). "In malignant melanomas, nuclear PAX2 expression strongly correlated with nuclear atypia and the degree of prominent nucleoli indicating an association of PAX2 with a more atypical cellular phenotype." (PMID 21876729, 2011). "Taken all our results together, we assume that PAX2 represents an interesting new therapeutic target molecule for the treatment of patients with melanoma or melanoma metastasis." (PMID 21876729, 2011). "In tissue samples of benign nevi and melanoma we identified PAX2 expression in nucleoli of melanocytes and melanoma cells." (PMID 21876729, 2011). "Weak nuclear Pax2 expression was found in melanocytes compared to stronger nuclear PAX2 expression in the melanoma cell lines IPC298 and G631." (PMID 21876729, 2011). "To investigate if PAX2 is involved in the chemoresistance of melanoma cells, we downregulated PAX2 protein expression in melanoma cells and treated the cells with the chemotherapeutic reagent cisplatin." (PMID 21876729, 2011). "An interesting future topic of our research will be to identify factors which are involved in the regulation of PAX2 in melanoma cells." (PMID 21876729, 2011). "To investigate the expression of PAX2 in tissue sections of benign nevi and malignant melanoma we performed double immunofluorescence analysis." (PMID 21876729, 2011). "To determine the role of PAX2 in the migration and invasion of melanoma cells we performed migration and invasion assays of SkMel5 cells after the knockdown of PAX2." (PMID 21876729, 2011). "In contrast to melanocytes and keratinocytes strong PAX2 expression was found in 5 of 6 melanoma cells." (PMID 21876729, 2011). "In summary, our data clearly demonstrate that PAX2 regulates ADAM10 expression in melanoma cells and to our opinion PAX2 represents a new interesting therapeutic target molecule in melanoma." (PMID 21876729, 2011). "Also, regulation of ADAM10 by PAX2 or miR-320a influences cisplatin sensitivity of melanoma cells and gastric cancer cells, respectively." (PMID 36699085, 2022). "Both malignant melanomas and intradermal nevi show heterogeneous PAX2 expression levels." (PMID 21876729, 2011).
melanoma (continued). "The inhibition of PAX2 in melanoma cells could reduce the proliferation, migration, invasion and chemoresistance of melanoma cells." (PMID 21876729, 2011). "Furthermore, the downregulation of PAX2 abrogated the chemoresistance of melanoma cells against cisplatin, indicating that PAX2 expression mediates cell survival and plays important roles during melanoma progression." (PMID 21876729, 2011). "Importantly, the downregulation of PAX2 completely inhibited the anchorage-independent cell growth of SkMel5 melanoma cells." (PMID 21876729, 2011). "With immunofluorescence analysis we could confirm that the downregulation of PAX2 led to a decreased ADAM10 expression in melanoma cells." (PMID 21876729, 2011). "Interestingly, the downregulation of PAX2 alone increased significantly the number of apoptotic melanoma cells." (PMID 21876729, 2011). "Quantification of immunofluorescence staining in melanocytes revealed that weak PAX2 expression correlated with weak ADAM10 fluorescence intensity and stronger immunofluorescence staining of PAX2 in melanoma cells was accompanied by increased ADAM10 expression." (PMID 21876729, 2011). "Notably, in melanoma patients larger PAX2 expressing nucleoli were detectable (merged image, yellow arrows)." (PMID 21876729, 2011). "We found: 1) Weak PAX2 expression in normal melanocytes and increased expression in melanoma cells." (PMID 21876729, 2011). "Therefore further experiments have to be performed to identify proteins which can be regulated through PAX2 and are responsible for the chemoresistance of melanoma cells against therapeutic reagents like cisplatin." (PMID 21876729, 2011). "Furthermore we are able to demonstrate that PAX2 expression in melanoma cells is involved in the migration, invasion and cell survival of melanoma cells." (PMID 21876729, 2011). "Importantly, the downregulation of PAX2 led to a significant reduction of the migratory and invasive capacity of melanoma cells." (PMID 21876729, 2011). "Importantly, PAX2 expression was visible in nucleoli of melanocytes (white arrows in the insets of PAX2 and merged images) and melanoma cells (yellow arrows in the insets of PAX2 and merged images)." (PMID 21876729, 2011). "Importantly, the downregulation of PAX2 by specific siRNA inhibited the anchorage independent cell growth and decreased the migratory and invasive capacity of melanoma cells." (PMID 21876729, 2011). "In summary, we can conclude that PAX2 expression is involved in melanoma cell survival." (PMID 21876729, 2011). "In addition, compared to control siRNA transfected melanoma cells, PAX2 downregulated melanoma cells showed a significant induction of apoptosis after the treatment with cisplatin." (PMID 21876729, 2011). "Therefore we wanted to characterize PAX2 expression in melanoma and investigate its role in the regulation of ADAM10." (PMID 21876729, 2011). "Compared to melanocytes increased PAX2 protein levels were detectable in melanoma cell lines." (PMID 21876729, 2011). "Further experiments in rodents will clarify, if the inhibition of PAX2 in melanoma cells will lead to a reduced melanoma growth in vivo and the development of small molecule inhibitors against PAX2 may represent a potential therapeutic option for the treatment of melanoma patients." (PMID 21876729, 2011). "Furthermore with in vitro assays we determined the role of PAX2 in melanoma progression." (PMID 21876729, 2011). "In human tissue samples we found co-expression of PAX2 and ADAM10 in melanocytes of benign nevi and in melanoma cells of patients with malignant melanoma." (PMID 21876729, 2011).
melanoma (continued). "To determine the expression levels of PAX2 and ADAM10 in keratinocytes, melanocytes and melanoma cells we performed Western Blot and immunofluorescence analysis." (PMID 21876729, 2011). "In summary, we can show that PAX2 can bind to the ADAM10 promoter and regulate ADAM10 protein levels in melanoma cells." (PMID 21876729, 2011). "To determine the localisation of PAX2 and ADAM10 we performed immunofluorescence analysis in melanocytes and melanoma cells." (PMID 21876729, 2011). "In contrast to nuclear PAX2, cytoplasmic and membranous ADAM10 expression was detectable in melanocytes and melanoma cells." (PMID 21876729, 2011). "In summary we can conclude, that melanocytes and melanoma cells in situ co-express ADAM10 and PAX2." (PMID 21876729, 2011). "In addition, with chromatin immunoprecipitation assay, PAX2 overexpression and PAX2 siRNA we present compelling evidence that PAX2 can regulate ADAM10 expression, a metalloproteinase known to play important roles in melanoma metastasis." (PMID 21876729, 2011). "Importantly, we present strong evidence, that PAX2 can regulate ADAM10 expression and that the downregulation of PAX2 inhibits the anchorage independent cell growth of melanoma cells." (PMID 21876729, 2011). "In contrast to PAX3, no data exist about the expression and function of PAX2 in melanoma development and progression." (PMID 21876729, 2011). "Therefore the downregulation of ADAM10 by PAX2 siRNA in melanoma cells will inhibit the production of soluble L1-CAM and therefore will inhibit the tumor-promoting function of soluble L1-CAM during melanoma progression." (PMID 21876729, 2011). "Only the melanoma cell line NW1539 expressed neither PAX2 nor ADAM10." (PMID 21876729, 2011).